RNU7-194P (RNA, U7 small nuclear 194 pseudogene)
Gene: Small nuclear RNA gene on chromosome 4 (150,209,706 to 150,209,768, forward strand). Ensembl gene ENSG00000238721.
Homologues: Orthologues: chimpanzee U7 (98% identical), macaque U7 (87% identical). Paralogues in human: RNU7-50P (81% identical), RNU7-10P (78% identical), RNU7-19P (78% identical), RNU7-34P (78% identical), RNU7-37P (78% identical), RNU7-7P (78% identical), RNU7-136P (76% identical), RNU7-167P (76% identical), RNU7-23P (76% identical), RNU7-26P (76% identical), RNU7-35P (76% identical), RNU7-40P (76% identical), and 142 more.